NEAT1 (nuclear paraspeckle assembly transcript 1)
Diseases named in the same sentence as NEAT1 in open-access papers (continued):
Sharing a sentence is not in itself a finding about the gene and the disease.
colorectal cancer (continued). "Whole blood NEAT1 expression was significantly higher in colorectal cancer patients than in NCs." (PMID 26552600, 2015). "Our study also demonstrated the prognostic potential of NEAT1 expression in colorectal cancer." (PMID 26552600, 2015). "Results proved that NEAT1expression was increased in 72.0% (172/239) colorectal cancer specimens compared with that in matched adjacent normal tissues, which indicated that the expression of NEAT1 was up-regulated in colorectal cancer compared with that in normal specimens." (PMID 26314847, 2015). "Therefore, further detection, analysis and study of the NEAT1 gene will provide a better understanding of the mechanism of colorectal cancer development, and will provide a more solid and reliable theoretical basis for the prevention and treatment of colorectal cancer." (PMID 39139172, 2024). "Consequently, NEAT1 can hold promise as a potential therapeutic target for colorectal cancer." (PMID 39830506, 2024). "However, whether NEAT1 can promote the progression of colorectal cancer through inflammatory, signaling is still unknown." (PMID 36213831, 2022). "The expression of NEAT1 in serum may be a marker for diagnosis and prognosis of colorectal cancer." (PMID 36213831, 2022). "Furthermore, we tested the expression of NEAT1 in colorectal cancer cell lines." (PMID 36213831, 2022). "To investigate whether NEAT1 promotes the progression of colorectal cancer by promoting an inflammatory response, we applied qRT-PCR, Western blot, and IHC assay, which showed that the expression of IL1B and caspase-1 increased in tumor tissues and cancer cells." (PMID 36213831, 2022). "However, the molecular mechanism by which NEAT1 contributes to colorectal cancer (CRC) remains unclear." (PMID 30407674, 2019). "To further validate that whole blood NEAT1 levels might accurately reflected the concentration in colorectal cancer tissues, we determined the relationship between NEAT1 expression in primary colorectal cancer tissues, para-tumor tissues with matched whole blood." (PMID 26552600, 2015). "Considering that NEAT1 acts as one of the main structural components in paraspeckles and possess a wide range of known or unknown function, its role in peripheral neutrophils of colorectal cancer patients is warranted." (PMID 26552600, 2015). "Our study provided the first evidence that NEAT1 was an independent prognostic factor of disease-free and overall survival for patients with colorectal cancer, suggesting that NEAT1 may be a potential predictive marker of tumor recurrence and prognosis for patients with colorectal cancer." (PMID 26314847, 2015). "The assays, like RNA pull-down in lung, gastric, and colorectal cancers, involve BC-IMPAD, NEAT1/miR-17-5p/TGFβR2, and FENDRR-GSTP1, respectively." (PMID 40861865, 2025). "A mixture of seven plant miRNAs inhibited proliferation of colorectal cancer cells and suppressed expression of the oncogenic lncRNAs MALAT1 and NEAT1." (PMID 40149445, 2025). "RNA pull-down assays have made it possible to understand the lncRNA–protein networks present in different malignancies, for instance, BC-IMPAD in lung cancer, NEAT1/miR-17-5p/TGFβR2 in gastric cancer, and FENDRR-GSTP1 in colorectal cancer." (PMID 40861865, 2025). "In colorectal cancer (CRC) tissues and cells, high expression of NEAT1 promotes resistance to 5-Fu in CRC cells by inducing autophagy." (PMID 38970092, 2024). "Conversely, silencing NEAT1 reduces autophagy by influencing ATG9A and ATG4B, which increases sensitivity to 5-fluorouracil in colorectal cancer." (PMID 39715205, 2024). "In colorectal cancer, this signaling is activated by the interaction of NEAT1 (nuclear enriched abundant transcript 1) with DDX5 to promote cancer and metastasis." (PMID 35954483, 2022). "NEAT1 can elevate the expression of some growth factors and transcription factors such as IGF2, GDNF, and BACH1, which facilitate the progression of colorectal cancer." (PMID 36011001, 2022).
colorectal cancer (continued). "Taken together, NEAT1 sponged miR-216b to activate YY1 to accelerate the ability of cell viability, apoptosis, and invasion on colorectal cancer cells." (PMID 36262350, 2022). "Therefore, NEAT1 may be a new marker and therapeutic target for colorectal cancer treatment." (PMID 36213831, 2022). "Depletion of NEAT1 by shRNA in LOVO and HCT 116 colorectal cancer cell lines downregulated IL-17RD mRNA expression, and decreased the tumor growth rate of LOVO xenografts." (PMID 33833999, 2021). "Even an aberrant expression of the lncRNAs NEAT1 and ROR has been documented in human tumor occurrence, such as breast, lung, ovarian, hepatocellular, and colorectal cancers." (PMID 34638805, 2021). "Notably, LncRNAs NEAT1, LOC152578, GLYCAM1, and SARS exhibited significantly reduced expression levels following aspirin treatment compared to untreated colorectal cancer cells." (PMID 40953835, 2025). "Firstly, the number of literature included in this meta-analysis was small; secondly, conducting the study solely in English limits its generalizability, as it excludes non-English research on NEAT1 in colorectal cancer." (PMID 39139172, 2024). "m6A in LncRNA NEAT1 was shown to exhibit oncogenic function in prostate cancer progression, METTL14-induced m6A process suppressed XIST expression, and suppresses proliferation and metastasis of colorectal cancer." (PMID 37773181, 2023). "In our study, we found that NEAT1 increased H3K27ac by affecting chromatin remodeling and led to an increase in acetylation levels of ALDH1 and c-Myc promoter regions, which increased their expression and thus enhanced the stemness of colorectal cancer cells." (PMID 33168814, 2020). "Lastly, the indirect control of NEAT1/KRAS was confirmed with small interfering RNA and antisense oligonucleotides both in vitro and in vivo, providing novel insight into the lncRNA‐based oncological therapeutic approach to treat human colorectal cancer." (PMID 30575330, 2019). "Therefore, NEAT1 could promote ZEB1 expression by targeting and inhibiting miR-448 and promote colorectal cancer proliferation and invasion in this way." (PMID 39830506, 2024). "Surprisingly in colorectal cancer, lncRNA RP1-85F18.6 is reported to promote proliferation and invasion as well as suppress pyroptosis whereas lncRNA nuclear paraspeckle assembly transcript 1 (NEAT1) could mediate ionizing radiation-induced pyroptosis relying on upregulation of GSDME expression." (PMID 35198448, 2022). "Multivariate analysis showed that NEAT1 expression could be a prognostic factor for overall survival of patients with colorectal cancer independent of gender, age, differentiation status, TNM stage, MSI, KRAS, BRAF and PIK3CA mutation." (PMID 26314847, 2015).
prostate carcinoma (85 papers, 2014 to 2025). A carcinoma that arises from epithelial cells of the prostate gland. "Recent studies have indicated that NEAT1 is significantly overexpressed in prostate cancer, and its expression level is closely associated with both the malignancy of the tumor and the prognosis." (PMID 41383743, 2025). "For example, overexpression of NEAT1, one of the m6A‐modified lncRNA, often leads to bone metastasis of cancer cells, and it significantly increases the risk of bone metastasis of prostate cancer through RNA–DNA interaction." (PMID 39187946, 2024). "The AR‐regulated lncRNA nuclear enriched abundant transcript 1 (NEAT1) can be recruited to the chromatin and epigenetically promotes the expression of prostate cancer‐associated genes." (PMID 33219721, 2021). "From a large compendium of ERα-regulated non-coding transcripts, we selected NEAT1 for a detailed biochemical and in vivo evaluation, based on an in silico approach that demonstrated a strong association of NEAT1 with prostate cancer progression." (PMID 25415230, 2014). "Analysis of two large clinical cohorts also revealed that NEAT1 expression is associated with prostate cancer progression." (PMID 25415230, 2014). "The mutation on the m6A sites of NEAT1 inhibited the metastasis of prostate cancer cells." (PMID 35789547, 2023). "Kaplan-Meier survival analysis of Tianjin Medical University data sets showed that high levels of NEAT1–1 or m6A on NEAT1–1 were associated with a shorter survival in prostate cancer patients with bone metastasis and overall survival in primary prostate cancer patients." (PMID 33308223, 2020). "An increased occurrence of mutations in the NEAT1 promoter was recently reported in patients who underwent androgen deprivation therapy in castration‐resistant prostate cancer highlighting the correlation between NEAT1 upregulation and resistance to androgen receptor antagonists." (PMID 30430751, 2019). "Notably, they included DMRs close to many genes previously implicated in prostate cancer (e.g., NEAT1, MTOR, RHCG, KCNC2, WT1, HOXC12, KMT2B)." (PMID 30318509, 2018). "Another mechanism associated with ERs in prostate cancer may involve interaction of ERs with nuclear paraspeckle assembly transcript 1 (NEAT-1), a transcriptional regulator which contributes to tumourgenesis." (PMID 27186486, 2016). "For example, NEAT1 will facilitate prostate cancer growth by activating the IGF1R/ATK signaling pathway." (PMID 39771106, 2024). "Through the act of miR-34a-5p and miR-204-5p sponging in prostate cancer cells, NEAT1 plays a functional role in the development of docetaxel resistance." (PMID 39512820, 2024). "The promoting effect of lncRNA NEAT1 on docetaxel resistance in prostate cancer was correlated with the inhibition of miR-204-5p." (PMID 38610003, 2024). "NEAT1's exosome transport expands its repertoire and allows its transfer between prostate cancer cells, which serves as a ceRNA for miR-205-5p." (PMID 38343745, 2024). "In docetaxel-resistant prostate cancer samples, NEAT1 was found to be overexpressed, as was indicated before." (PMID 39512820, 2024). "Other researchers have confirmed the oncogenic role of NEAT1 in other tumors, including breast, lung, hepatocellular, ovarian, and prostate cancers." (PMID 38577722, 2024). "For example, NEAT1 drives prostate cancer progression through transcriptional regulation of prostate cancer-specific genes." (PMID 38177154, 2024). "Another example is the lncRNA NEAT1, which is overexpressed in docetaxel-resistant prostate cancer cells." (PMID 39512820, 2024). "In this context, NEAT1/m6A levels were positively correlated with prostate cancer progression and bone metastases onset, and negatively correlated with patient survival." (PMID 37143733, 2023). "There is also report stating that lncRNA NEAT1 depletion inhibits aerobic glycolysis of prostate cancer cells accompanied by the reduction of lactate levels in the medium." (PMID 37234237, 2023).
prostate carcinoma (continued). "Based on validation from the GEPIA2 and UALCAN online databases, SNHG3 and NEAT1 were significantly up-regulated in prostate cancer." (PMID 36890836, 2023). "A number of well-known oncogenic lncRNAs in other cancers such as DANCR, MALAT1, CCAT1, PVT1, TUG1 and NEAT1 have also been shown to act as oncogenes in prostate cancer." (PMID 37025585, 2023). "NEAT1/m6A has been reported to facilitate the oncogenic function of the novel CYCLINL1/CDK19 complex in patient-derived metastatic bone xenograft (PDX) and that NEAT1/m6A plays a vital role in regulating the progression of prostate cancer." (PMID 37143733, 2023). "Previous studies have shown that lncRNA NEAT1 is involved in regulating the development and progression of cervical cancer, pancreatic cancer, liver cancer, prostate cancer and multiple myeloma." (PMID 35659599, 2022). "NEAT1 is shown to regulate the expression of prostate cancer genes and promotes the development of prostate cancer by changing the epigenetic landscape of the target gene promoter." (PMID 35103065, 2022). "After detecting the expression of NEAT1 in tissues and cell lines, they observed that NEAT1 was significantly upregulated in prostate cancer tissues and cell lines compared with normal tissues and the normal prostate epithelial cell line." (PMID 36011001, 2022). "Nuclear-rich transcriptase 1 (NEAT1), a potential target of estrogen receptor alpha (ERα), is significantly overexpressed in prostate cancer." (PMID 35103065, 2022). "Studies have revealed that there are m6A modification sites on lncRNA NEAT1, which is related to bone metastasis in prostate cancer." (PMID 34777473, 2021). "The oncogenic effects of NEAT1 have been reported to be influenced by the CDC5L-AGRN transcriptional regulation circuit in prostate cancer." (PMID 33428596, 2021). "As an oncogene, NEAT1 promotes docetaxel resistance in prostate cancer by regulating acyl-CoA synthetase long chain family member 4 (ACSL4) via sponging miR-34a-5p and miR-204-5p." (PMID 33738254, 2021). "For instance, the m6A modification of the NEAT1 lncRNA promoted the bone metastasis of prostate cancer by facilitating the CYCLINL1-CDK19 interaction, which was required for the ser2 phosphorylation of Pol II." (PMID 34458149, 2021). "Recently, many ncRNAs, such as MALAT1, NEAT1, MIR25, and LET-7, are found to be associated with prostate cancer." (PMID 34576294, 2021). "To further substantiate the survival significance of m6A on NEAT1–1, we analyzed the NEAT1–1 expression, m6A level of NEAT1–1 and its correlations with clinical behaviors of prostate cancer patients in our bone-metastasis cohort." (PMID 33308223, 2020). "In breast and prostate cancers, NEAT1 stimulates the TCA cycle by promoting the use of free fatty acids as fuel." (PMID 33123488, 2020). "Box plot analysis showed that m6A level of NEAT1–1 was significantly higher in bone metastatic prostate cancer samples than primary prostate cancer or adjacent normal samples in two independent data sets with FFPE samples and data set with frozen samples." (PMID 33308223, 2020). "The m6A level of NEAT1–1 was positively related to prostate cancer progression, bone metastasis and negatively related to patients’ survival." (PMID 33308223, 2020). "In the dataset, NEAT1–1 expression was significantly higher in prostate cancer compare to normal tissues." (PMID 33308223, 2020). "NEAT1 was significantly elevated in docetaxel-resistant prostate cancer cell lines compared to docetaxel-sensitive lines." (PMID 35582574, 2019). "Nuclear enriched abundant transcript 1 (NEAT1) was identified as the most significantly over-expressed lncRNA in prostate cancer by using a combination of chromatin immunoprecipitation (ChIP) and RNA-sequencing data." (PMID 31760932, 2019). "For instance, CTBP1-AS, a lncRNA that promotes prostate cancer, is androgen responsive, whereas NEAT1, a lncRNA that also promotes prostate cancer, is oestrogen responsive." (PMID 30598023, 2018).
prostate carcinoma (continued). "NEAT1 has also been shown to modulate prostate cancer-specific gene expression through chromatin modifications and thus contributes to cancer progression." (PMID 28615056, 2017). "NEAT1 was also found to positively regulate the progression of prostate cancer by turning on transcription of prostate cancer related genes epigenetically." (PMID 28288210, 2017). "Nuclear enriched abundant transcript 1 (NEAT1) was identified as a potential prognostic marker and an important regulator for the maintenance of prostate cancer." (PMID 29050268, 2017). "In prostate cancer, NEAT1 and PRNCR1 are key elements of estrogen and androgen signaling, respectively." (PMID 27340923, 2016). "Although several previous studies have reported the important roles of NEAT1 as biomarker in acute promyelocytic leukemia and prostate cancer, little is known about the role of lncRNA NEAT1 in OvCa." (PMID 26863568, 2016). "Recent studies showed that NEAT1 is upregulated and possesses oncogenic properties in various cancers such as lung, breast and prostate cancer." (PMID 26822763, 2016). "In prostate cancer NEAT1 are involved in gene transcription of cancer progression genes by interacting with histones and/or chromatin-modifying proteins, which supports our findings." (PMID 25887545, 2015). "Among putatively ERα-regulated intergenic long non-coding RNAs (lncRNAs), we identified nuclear enriched abundant transcript 1 (NEAT1) as the most significantly overexpressed lncRNA in prostate cancer." (PMID 25415230, 2014). "We selected the top ten genes that were significantly correlated to NEAT1 expression across all prostate cancer concepts." (PMID 25415230, 2014). "This suggests that NEAT1 transcriptionally regulates a compendium of genes known to be involved in prostate cancer progression." (PMID 25415230, 2014). "We were particularly interested in identifying genes significantly deregulated in prostate cancer and positively correlated with ERα and NEAT1 expression." (PMID 25415230, 2014). "NEAT1 expression independently was sufficient to activate prostate cancer genes in an AR-independent manner." (PMID 25415230, 2014). "We observed that relative mRNA levels of these NEAT1-ERα signature-selected genes revealed significant upregulation in prostate cancer." (PMID 25415230, 2014). "Analysis of the top 1,000 genes of the NEAT1 signature revealed that this signature is upregulated in prostate cancer data sets when compared with other cancer data sets." (PMID 25415230, 2014). "We identified nuclear enriched abundant transcript 1 (NEAT1) long non-coding RNA (lncRNA) as a potential target of ERα and as an important mediator for maintenance of prostate cancer." (PMID 25415230, 2014). "To better understand the physiological role of NEAT1 in the context of ERα in prostate cancer, we first determined the levels of NEAT1 in VCaP cells overexpressing ERα." (PMID 25415230, 2014). "Prostate cancer cells expressing high levels of NEAT1 were recalcitrant to androgen or AR antagonists." (PMID 25415230, 2014). "We next sought to understand the physiological role of NEAT1 and to determine the downstream targets of the ERα-NEAT1 axis in prostate cancer." (PMID 25415230, 2014). "Among the putatively ERα-regulated intergenic lncRNAs, we identified NEAT1 as the most significantly overexpressed lncRNA in prostate cancer versus benign prostate in our patient cohort (73 samples)." (PMID 25415230, 2014). "We show here that NEAT1 regulates expression of prostate cancer genes by altering the epigenetic landscape at target gene promoters to favour transcription." (PMID 25415230, 2014). "We observed that in a panel of prostate cancer cell lines, ERα overexpression and E2 treatment upregulated NEAT1 transcript levels in a time-dependent manner." (PMID 25415230, 2014).